INS (insulin)
Diseases named in the same sentence as INS in open-access papers (continued):
Sharing a sentence is not in itself a finding about the gene and the disease.
Hypoglycemia (continued). "Although hypoglycemia is not a side effect of pramlintide, caution is needed when used with therapies with known hypoglycemic effects, such as insulin." (PMID 38338796, 2024). "Factitious hypoglycemia was ruled out during her hospital stay, where she continued to have hypoglycemic episodes without any exogenous insulin administration or use of hypoglycemic agents." (PMID 38817472, 2024). "Unlike sulfonylureas or insulin, which are associated with higher rates of hypoglycemia, DPP-4 inhibitors such as alogliptin generally exhibit a low risk of hypoglycemia, and this was observed in the EXAMINE trial as well." (PMID 39768866, 2024). "In patients without episodes of hypoglycemia, we caution that the required intravenous insulin dose will decrease after the administration of the insulin analog." (PMID 38365663, 2024). "Second, the impaired glucose homeostasis is due to an absent adrenaline elevation in response to insulin-evoked hypoglycemia, as observed for the impaired autonomous failure in HAAF patients." (PMID 39375537, 2024). "The aim of the present study was to analyze, in patients admitted for HHC, the risk factors for the occurrence of hypoglycemia and the mid- and long-term prognostic value of hypoglycemia during the treatment of HHC, both in the IIITP and in the later subcutaneous insulin therapy phase (LSITP)." (PMID 38594758, 2024). "In other words, a lack or minimal presence of insulin-positive cells was observed in recipients without hypoglycemia and persistent bioluminescence signals." (PMID 38920672, 2024). "Level 2 hypoglycemia during IV insulin administration was not different between the study groups (p = 0.806)." (PMID 39136541, 2024). "Insulin-induced hypoglycemia tests were conducted in all twenty-four patients, and none of them exhibited stimulated growth hormone secretion." (PMID 38828392, 2024). "Somewhat conversely, a study with 14 participants demonstrated that treating C-peptide-positive T1D with liraglutide did lower hemoglobin A1C, body weight, and insulin use but found no significant change in hypoglycemia." (PMID 39594662, 2024). "Histological examination of the grafts revealed a lack or minimal presence of insulin-positive cells in recipients without hypoglycemia and persistent bioluminescence signals." (PMID 38920672, 2024). "In addition to severe hypoglycemia, DKA is a potential complication of insulin failure during pregnancy." (PMID 38664886, 2024). "Further examination of daily glycemic profiles revealed that the system had activated the “safe meal bolus” function, resulting in a lower insulin dose being administered to avoid postprandial hypoglycemia, rather than using the ICR setting at that time." (PMID 38592281, 2024). "Because the patient's history and presentation were consistent with PBH, further evaluation for other etiologies of hypoglycemia (eg, morning cortisol, insulin antibodies, 24-hour fast) was not pursued." (PMID 39444516, 2024). "While previous studies identified the serotonin 5-HT3 receptor in β cells as a mediator of serotonin-induced insulin secretion, here we demonstrate that serotonin receptor 3 antagonist (ondansetron) was not able to block serotonin-induced hypoglycemia." (PMID 39264731, 2024). "Although overdosage of insulin secretagogues should be noted in relation to hypoglycemia, to our knowledge, the occurrence of hypoglycemia by TGR agonists has not been reported." (PMID 38332164, 2024). "In insulin-treated diabetic rats, adrenal medullary TH protein level was increased after seven episodes of hypoglycaemia despite no increase in TH mRNA levels." (PMID 38392992, 2024). "To induce hypoglycemia, we injected α-A2AR-KO and control mice with insulin (1 U/kg, i.p.)." (PMID 38879678, 2024). "To address the possibility that the more pronounced hypoglycemia in animals lacking TRPCs results from increased peripheral insulin sensitivity, we subjected mice to an oral glucose tolerance test." (PMID 39375537, 2024).
Hypoglycemia (continued). "Liraglutide is known to work by stimulating the secretion of insulin whilst supressing glucagon secretion in a glucose-dependent manner and has been reported not to induce hypoglycaemia." (PMID 36773648, 2023). "Chronic elevated levels of insulin and proinflammatory cytokines could explain the negative regulation of cortisol secretion, where increased insulin causes a deficient cortisol response to hypoglycemia, as occurs in patients with ME/CFS assessed using the insulin-induced hypoglycemia test." (PMID 37718435, 2023). "In the SURPASS study, with a high margin over insulin and GLP-1RAs, tirzepatide was shown to significantly control blood glucose and body weight without causing hypoglycemia." (PMID 37096236, 2023). "Patients with hypothyroidism require lower doses of insulin due to the low production of hepatic glucose, and when the need for exogenous insulin is not adapted, symptomatic hypoglycemia ensues." (PMID 36983604, 2023). "Insulinoma cells can sustain the release of insulin and are not affected by blood glucose levels, which often leads to frequent episodes of hypoglycemia." (PMID 37033225, 2023). "Among these patients, those who had hypoglycemic events were more likely to be of advanced age, African American, treated with insulin, or hypertensive, and to have had a previous stroke, or have end-stage renal disease than patients without hypoglycemia." (PMID 37372995, 2023). "Current literature supports the fact that structured educational programs can have an impact on people with T2DM who use insulin, improving metabolic control, without producing hypoglycemia." (PMID 37377235, 2023). "Intranasal insulin is administered instead of peripheral insulin to promote direct entry to the brain through the bulk flow, olfactory nerve channels, and trigeminal perivascular channels, avoiding the BBB limitations and potential hypoglycemia." (PMID 37569861, 2023). "In a replicate study, cows experienced decreased insulin sensitivity as demonstrated by an intravenous glucose tolerance test, but did not develop hypoglycemia." (PMID 37727248, 2023). "As a result, there is an absolute lack of insulin leading to disturbances in carbohydrate metabolism (hyper and hypoglycemia)." (PMID 37570425, 2023). "In fact, DPP-4 inhibitors are now replacing the use of sulphonylureas as insulin-releasing agents due to their insulin-tropic effect, and notably because DPP-4 inhibitors reduce the intrinsic risk of low blood sugar or hypoglycaemia." (PMID 37287751, 2023). "Because IGF2 is less effective than insulin in stimulating glucose uptake, even a large dose of intranasal IGF2 would be unlikely to cause hypoglycemia." (PMID 36971212, 2023). "Another limitation is that we did not analyze the effects of insulin on arrhythmias because there were controversies regarding the potential implication of hypoglycemia." (PMID 37893478, 2023). "However, it is worth mentioning that in the insulin tolerance test, all F1 CTRL females had to be removed from the experiment at minute 60 due to severe hypoglycemia." (PMID 37887423, 2023). "The rate for nocturnal non-severe hypoglycemia was 54% lower during treatment with insulin analogs than human insulins, equivalent to an ARR of 3.4 events per patient-year (p < 0.001)." (PMID 38089060, 2023). "In normal conditions, glucagon is known to increase insulin secretion in the postprandial phase but not when it is secreted in response to hypoglycemia." (PMID 37432389, 2023). "Here, we report a case of a healthy non-diabetic male in his 50s presenting with recurrent episodes of hypoglycemia with no prior exposure to exogenous insulin." (PMID 37525774, 2023). "Such harms include hypoglycemia because of the administration of fast-acting insulin to a patient who was not on insulin and worsening of atrial fibrillation for a patient whose warfarin prescription was omitted." (PMID 37968602, 2023).
Hypoglycemia (continued). "Patients treated with insulin are particularly vulnerable to hypoglycemia, especially those who use vials and syringes rather than disposable pens." (PMID 37372995, 2023). "Forty-two children with T1DM on insulin pump for at least 1 year were assessed during the period from June 2020 to May 2021 for insulin requirements, insulin-pump problems, frequency of diabetic-ketoacidosis (DKA), hypoglycemia and HbA1C." (PMID 38012643, 2023). "IAS is characterized by recurrent spontaneous hypoglycemia, the presence of insulin autoantibodies in the body, significantly elevated serum insulin, and no history of exogenous insulin injections." (PMID 36844104, 2023). "The PI3K-AKT-mTOR pathway hyperactivation leads to increased intracellular glucose uptake and reduced hepatic gluconeogenesis, with net hypoglycaemia in the absence of serum insulin." (PMID 37048663, 2023). "Through effects on insulin-secreting β cells, EPE increases the release of endogenous insulin via insulin-p-Akt-p-FoxO1 and/or via hepatic p-AMPK to suppress the hepatic PEPCK pathway and improve muscle membrane GLUT4 protein levels, thereby producing hypoglycemia." (PMID 37850072, 2023). "Despite hypoglycemic mortality rates being not clear, insulin and insulin secretagogue-induced hypoglycemia can be fatal in T2DM." (PMID 37633882, 2023). "On the other hand, there was no statistical difference between BIF and once-daily insulin in terms of level 1 hypoglycemia, nocturnal level 1 hypoglycemia, and level 2 hypoglycemia." (PMID 38206709, 2023). "There was no significant increase in hypoglycemia occurrence after adding GLP-1 to an already effective antidiabetic treatment that included either sulfonylurea or insulin." (PMID 38169925, 2023). "An increase in HSS was observed during hypoglycaemia induction for both insulin products independent of dose level." (PMID 37308751, 2023). "In our cohort, no cases of hypoglycemia were recorded in either group, this probably due to the fact that there was no need for intensification of insulin treatment." (PMID 37775682, 2023). "However, combination therapy of basal insulin and GLP-1 RA still had low episodes of hypoglycemia in both studies (1.9 %)." (PMID 36897731, 2023). "These patients were more obese and insulin-resistant as compared to those who did not develop hypoglycemia." (PMID 38068304, 2023). "Although the frequency of hypoglycemia was generally low in clinical trials testing GLP-1 receptor agonists in combination with sulphonylurea (with or without metformin) or insulin, it was higher compared to placebo." (PMID 37920618, 2023). "Obese women with PCOS who developed reactive hypoglycemia had a higher cumulative insulin response as compared to those who did not develop hypoglycemia." (PMID 38068304, 2023). "Consistent with this, dose-response studies have shown that higher insulin levels during hypoglycemia do not further reduce EGP, suggesting that a modest gain in hepatic insulin sensitivity in FAST would not be expected to account for a 60% reduction in EGP." (PMID 37166980, 2023). "When exercise is not planned and/or changes in insulin were not made, food intake is an important tool to prevent hypoglycemia." (PMID 36964201, 2023). "Previous work demonstrated a pattern of QT interval prolongation, premature atrial contractions, premature ventricular contractions, and first-degree heart block following induction of hypoglycemia in insulin-injected non-diabetic rats." (PMID 37200277, 2023). "On the contrary, higher intraoperative immunoreactive insulin/glucose ratio and 24-h urine epinephrine levels, but not 24-h urine norepinephrine levels, were predictive factors for post-adrenalectomy hypoglycemia." (PMID 36982228, 2023). "Hybrid closed-loop insulin delivery achieved superior glycemic control to SAP therapy (TIR 79.9% vs. 71.4%), without increasing the risk of hypoglycemia." (PMID 36983941, 2023).
Hypoglycemia (continued). "Dose reduction of meal-related bolus insulin does not prevent late-onset (nocturnal) hypoglycaemia in people using first-generation long-acting insulins." (PMID 36879098, 2023). "These drugs improve glycemic control through the regulation of glucose‐dependent insulin secretion protecting pancreatic beta cells without inducing hypoglycemia." (PMID 35485604, 2023). "The characteristic of hyperinsulinaemic hypoglycaemia is measurable, not necessarily high, insulin concentrations which are inappropriately high in the presence of hypoglycaemia." (PMID 37892096, 2023). "The closed-loop system improved the proportion of time spent in target glucose range by 35 percentage points (an additional 8 h per day), and reduced mean glucose, compared with standard insulin therapy, without increasing the time spent in hypoglycemia." (PMID 36631592, 2023). "This leads to fasting hypoglycemia with low ketone levels in the absence of elevated insulin and C-peptide values." (PMID 37630734, 2023). "When the best possible treatment was selected for each subject, the rate of severe hypoglycemia was reduced to 0.7 episodes per patient-year, as opposed to 1.1 for the insulin analog regimen and 1.6 for treatment with human insulins." (PMID 38089060, 2023). "The oral glucose tolerance test with measurement of glucose and insulin at every time point is most frequently used to establish the diagnosis of hypoglycemia in CPSS, with a typical pattern of postprandial hyperglycemia followed by hypoglycemia." (PMID 37664849, 2023). "This case report highlights the importance of IAA titers in first-line investigations for hypoglycemia in a non-diabetic patient with strikingly high blood insulin levels and discusses the potential relationship between IAS and alpha-lipoic acid." (PMID 37727171, 2023). "Patients who used regular human insulin presented higher percentages of time with hypoglycemia < 70 mg/dL in P1, but not in P2, than those on rapid-acting insulin analogs did (13 [6-19.5] % vs. 6 [3.5-11]%, p = 0.035)." (PMID 36468924, 2023). "We report a case of a previously healthy Indian male presenting with recurrent episodes of hypoglycemia with no prior exposure to exogenous insulin." (PMID 37727171, 2023). "By restoring the impaired incretin response and promoting glucose-dependent insulin secretion, GLP-1RAs effectively lower blood sugar levels without causing hypoglycemia." (PMID 37456411, 2023). "By temporarily suspending insulin delivery, SAP can avoid (or limit) the severity of hypoglycemia." (PMID 37942482, 2023). "Metformin can effectively lower neonatal birth weight and the incidences of macrosomia, neonatal hypoglycemia, and NICU admission compared with insulin without an increased risk of neonatal adverse outcomes." (PMID 36593391, 2023). "Administering more than 10 times the therapeutic dose of insulin is extremely rare in diabetic dogs and is life threatening with hypoglycemia and seizures if not accompanied by appropriate treatment." (PMID 38026640, 2023). "Studies demonstrated that GLP-1 receptor agonists can delay the onset of insulin therapy without the typical side effects of hypoglycaemia or weight gain and even better blood pressure control." (PMID 36768000, 2023). "Generally, single use will not lead to hypoglycemia, but if combined with sulfonylureas or insulin, attention should be paid to prevent hypoglycemia." (PMID 36843578, 2023). "An elderly patient with an intrathoracic neoplasm and hypoglycemia underwent various tests: insulin autoantibodies and fasting test were both negative." (PMID 37373678, 2023). "In concordance with these results, a prospective 6‐month study including 14 children with T1D younger than 6 years old who received insulin glargine showed a drop in the average HbA1c without increasing the frequency of severe hypoglycemia." (PMID 36800034, 2023).
Hypoglycemia (continued). "This case thus highlights the importance of including IAA titers in first-line investigations for hypoglycemia in a non-diabetic patient with strikingly high blood insulin levels." (PMID 37525774, 2023). "ECG heartbeats were extracted from 91 male Sprague-Dawley rats (54 non-diabetic, 37 diabetic), 24 of which died (14 non-diabetic, 10 diabetic) during insulin-induced hypoglycemia clamp experimentation." (PMID 37200277, 2023). "We conducted this study to examine the risk of hospitalization for COPD, pneumonia, ventilator use, lung cancer, hypoglycemia, and mortality with and without insulin use in people with T2D and COPD." (PMID 37242426, 2023). "Still, we acknowledge that the hypoglycaemia was induced under experimental and not real-life conditions, when insulin concentrations would be lower." (PMID 36648553, 2023). "The effects of glucose effectiveness, the insulin-independent mechanism of glucose disposal, on hypoglycemia have not yet been fully investigated." (PMID 36837857, 2023). "Prolonged fasting can lead to hypoglycemia only when there is a deficit in the ability to maintain normoglycemia, such as too much insulin." (PMID 36844104, 2023). "Intranasal insulin is safe to administer, and a systematic review found that no adverse effects or hypoglycaemia occurred when Intranasal insulin of doses between 10 and 160 IU occurred in 1092 participants." (PMID 38068438, 2023). "The resting HR and blood pressure did not change significantly during insulin‐induced hypoglycaemia." (PMID 36459572, 2023). "Although no recurrences of hypoglycemia were present in the two cases studied, insulin autoantibodies remained positive for the previous follow-up sessions, which turned negative only three years after discharge." (PMID 37587407, 2023). "There were no congenital malformations or cases of severe neonatal hypoglycemia, which suggested that insulin detemir was as good as NPH in terms of safety." (PMID 37775682, 2023). "Stricter system settings (active insulin time (AIT) of 2 h and glucose target of 100 mg/dL) were associated with better glycemic control, without an increase in severe hypoglycemia." (PMID 38068733, 2023). "Further, glimepiride added to insulin group showed a significant decrease in insulin doses, incidence of hypoglycemia and no weight gain." (PMID 36624650, 2023). "In our patient, large diurnal fluctuations in insulin levels and mainly fasting hypoglycaemia were observed, but without the clinical signs typical for hypoglycaemia." (PMID 36331627, 2023). "However, somatostatin analogues exert their therapeutic effect by inhibiting insulin and GLP-1 secretion to prevent postprandial hypoglycemia." (PMID 36748934, 2023). "GLUT1 expression or activity is independent of insulin signaling, while hypoglycemia can induce GLUT1 upregulation with no change in glucose uptake." (PMID 37858199, 2023). "Of note, intranasal insulin, unlike peripheral insulin administration, has the advantage of bypassing the BBB and avoiding the risk of hypoglycemia." (PMID 36671568, 2023). "Blood glucose of diabetic rats pre-treated with iodine prior to the administration of insulin showed a decrease in blood glucose within 7 h as compared to rats without pre-treatment, whereby no hypoglycemia was observed." (PMID 36979643, 2023). "The Canadian Agency for Drugs and Technologies in Health (CADTH) recommends FSL reimbursement for T1DM and T2DM patients requiring multiple daily insulins injections and experiencing recurrent hypoglycemia, despite frequent SMBG and efforts to optimize insulin management." (PMID 38001509, 2023). "The results showed that he had hypoglycemia of 25 mg/dL, insulin level of 33.65 μU/mL, c-peptide level of 3.3 ng/mL, negative circulating sulfonylurea levels, and insulin antibody levels." (PMID 37026903, 2023). "Hypoglycemia in biguanides exposure is not common because they increase insulin sensitivity and does not increase insulin release." (PMID 37024869, 2023).